PCK2 (phosphoenolpyruvate carboxykinase 2, mitochondrial)
Diseases named in the same sentence as PCK2 in open-access papers (continued):
Sharing a sentence is not in itself a finding about the gene and the disease.
cancer (74 papers, 2012 to 2026). A tumor composed of atypical neoplastic, often pleomorphic cells that invade other tissues. "Mitochondrial phosphoenolpyruvate carboxykinase (PCK2), a mitochondrial isoenzyme, supports the growth of cancer cells under glucose deficiency conditions in vitro." (PMID 38890507, 2024). "Only limited data exist on the association of PCK2 expression and prognosis in different cancer entities." (PMID 32777161, 2020). "The results showed that the top genes positively associated with PC1 included RBP4, SLC27A5, and PCK2, all of which were known tumor-related genes and correlated with cancer patients’ survival." (PMID 32231683, 2020). "Among the PRCa genes expressed at the protein level are transcriptional regulators (Hdac2 and Hmga2), cancer-linked genes (Klf4 and Kit), and genes involved in glycolysis and pyruvate metabolism (Hk1, Eno2, and Pck2)." (PMID 22305566, 2012). "Thus, the diversity of PCK2 expression in different cancer models make it a challenging therapeutic target and it is required to fully investigate the underlying molecular mechanisms of PCK2-mediated tumor development in different tissues and disease stages." (PMID 39193344, 2024). "In recent years, Phosphoenolpyruvate carboxykinase 2 (PCK2) has emerged as a potential candidate in cancer research." (PMID 39744481, 2025). "Patients at more advanced cancer stages tended to have lower expression levels of PCK2, and the expression of PCK2 was also tied to age, gender, and AFP (Alpha-fetoprotein) level." (PMID 38890507, 2024). "The tumor-promoting or tumor-suppressive roles of PCK2 in different studies depend on the cancer type and context." (PMID 39193344, 2024). "Mitochondrial PEP-carboxykinase (PCK2) plays a key role in cancer cell MR via glucose-independent cell growth and metabolic stress resistance in NSCLC." (PMID 38841622, 2024). "A role for PCK isoform 2 (PCK2) in reverse glycolysis has been reported only in cancer cells, where PCK2 fuels lipid and nucleotide synthesis in glucose-deprived conditions." (PMID 38783087, 2024). "ECs and multiple cancer cells express PCK2, at elevated levels in glucose-deprived conditions, but otherwise, both cell types exhibit several differences." (PMID 38783087, 2024). "Gluconeogenesis is the synthesis of glucose from non-carbohydrate precursors and can antagonize aerobic glycolysis in cancer via the gluconeogenesis-related key enzymes PCK1/PCK2, FBP, and G6PC." (PMID 38017546, 2023). "Cancer cells have been found to generate critical metabolites using shortened gluconeogenesis versions by expressing phosphoenolpyruvate carboxykinase (PEPCK, PCK1, or PCK2)." (PMID 36837801, 2023). "Overexpression of PCK2 has been identified in cancer cells in many anatomical sites in humans, including the thyroid, breast, lung, and urinary tract, according to The Cancer Genome Atlas (TCGA) analysis." (PMID 35757841, 2023). "Overexpression of PCK2 has been identified in many human cancers and demonstrated to be important for the survival program initiated upon metabolic stress in cancer cells." (PMID 35757841, 2023). "A clue to the mechanism for the integrative role of PCK2 in cancer metabolism arises from its transcription regulation by ATF4 under nutrient stress." (PMID 35681299, 2022). "Upregulation of the expression of either the cytosolic isoform, PCK1, or the mitochondrial isoform, PCK2, is dependent on cancer type." (PMID 33946927, 2021).
cancer (continued). "PCK2 also was shown to participate in OXPHOS in tumor repopulating cells and dysregulation of PCK2 was found in many cancer types." (PMID 37304670, 2021). "In a glucose-deprived setting, cancer cells have the ability to switch to using glutamine as a substrate and engage the early steps of gluconeogenesis through regulation of mitochondrial PCK2." (PMID 33306983, 2021). "In summary, gluconeogenesis enzymes PCK1 and PCK2 are expressed in cancers arising from diverse tissues, contrary to previous assumptions." (PMID 33540663, 2021). "The diverse functions of PCK1 and PCK2 in cancer cells, either promoting partial gluconeogenesis, regulating the TCA cycle or in moonlighting, nonclassical functions are not fully elucidated." (PMID 33540663, 2021). "Subsequently, PCK2 or PCK1 have been found to be active especially under conditions of glucose deprivation to promote cell survival or proliferation in diverse cancer types." (PMID 33540663, 2021). "The endoplasmic reticulum stress mediator cyclic AMP-dependent transcription factor ATF4 plays an important role in the activation of PCK2 expression upon glucose or glutamine deprivation in cancer cells." (PMID 33540663, 2021). "The downstream metabolic pathways fueled by PCK1 or PCK2 in cancer cells include the biosynthesis of the phospholipid glycerol backbone, serine, or ribose." (PMID 32777161, 2020). "Differential regulation of downstream genes in CMTs with the PIK3CA (H1047R) mutation, such as up-regulated PCK2 and down-regulated CDKN1B, allows cancer cells to utilize an alternative catabolic pathway." (PMID 31842489, 2019). "A number of studies now report a role for PEPCK-M (Pck2) in proliferative cell growth and it has become an attractive metabolic drug target in relation to several cancers." (PMID 31237922, 2019). "In a previous study, PCK2 activation was found to be important for the response to environmental stresses such as glucose depletion, conferring an adaptive ability on cancer cells." (PMID 30380689, 2018). "Elevated expression of PCK2 has been found in various tumors according to the results of The Cancer Genome Atlas project." (PMID 29262588, 2017). "The hypoxia-inducible factors HIF-1a and EPAS1 could regulate PCK2 expression under glucose limitation and PCK2 is required of glucose-independent cancer cell proliferation and tumor growth in vivo." (PMID 39744481, 2025). "To date, there has been little focus on PCK2 in the context of cancer." (PMID 39193344, 2024). "PCK2 promotes cancer growth in vivo by mediating tumor cell glucose restriction adaption." (PMID 38890507, 2024). "As pointed out in a previous study that PEPCK‐mediated metabolic remodeling contributes to histone methylation, which regulates cancer progression, we first pointed out that IGF2BP3lac mediated PCK2 upregulation promotes the whole levels of m6A‐modification and the anti‐TKI drug phenotype." (PMID 39450426, 2024). "The expression of PCK2 is different in a series of cancers and adjacent tissues." (PMID 38890507, 2024). "PCK1 and PCK2 have also been reported to be critical for the growth of certain cancers." (PMID 37904164, 2023). "Given their central position in carbon metabolism, regulating the OAA-PEP-pyruvate node, PCK1 or PCK2 might play an important role in modulating metabolism and cell fate decisions in many different cancer types, especially in a glucose-poor microenvironment." (PMID 33540663, 2021).
cancer (continued). "Thus, oncogenic and nutrient-sensing pathways converge on the regulation of PCK1 and PCK2 in cancer cells, which ensures their flexible expression according to the nutritional state and metabolic demands." (PMID 33540663, 2021). "However, in liver cancer and hepatocellular carcinoma, PCK1 or PCK2 have been found to be downregulated and to inhibit cancer cell proliferation or tumor growth in vivo." (PMID 33540663, 2021). "The downstream metabolites generated via PCK1 or PCK2 in glucose-deprived cancer cells include all the biosynthetic precursors classically considered to be derived from glucose: the phospholipid glycerol backbone, serine and glycine used for purine biosynthesis and ribose phosphate." (PMID 33540663, 2021). "Additionally, it was demonstrated that PCK2 up-regulation is a novel metabolic adaptation in cancer." (PMID 34203686, 2021). "Moreover, PCK2 was shown to directly impact TCA cycle function in cancer cells by catabolizing OAA generated from glutamine, although this function was studied in high glucose." (PMID 33540663, 2021). "Moreover, PCK2 was shown to directly impact tricarboxylic acid (TCA) cycle function in cancer cells by catabolizing OAA generated from glutamine." (PMID 32777161, 2020). "The overall effect of cancer driver mutations on GLUT1 and PCK2 expression appeared limited and may only partially explain the observed interpatient variability." (PMID 32777161, 2020). "It was recently reported that PCK2 is highly expressed in different cancer cells and samples." (PMID 29137367, 2017). "However, further research is warranted to clarify the role of PEPCK (PCK1 or PCK2) in cancer cell metabolism." (PMID 26682254, 2015). "This suggests that the role of PCK2 may vary depending on the cancer type and context." (PMID 40182032, 2025). "In this light, targeting PCK2 may be an effective strategy for certain cancer subtypes." (PMID 39193344, 2024). "Others have reported cancer cells that perform glutamine-derived gluconeogenesis increase NADPH production for fatty acid synthesis and other biosynthetic precursors through PCK2 activity." (PMID 41542490, 2026). "PCK2 mediates transport of oxaloacetate from the TCA cycle and decarboxylation to PEP, which has been recognized as an important metabolic adaptation for cancer cells in response to nutrition deprivations." (PMID 39193344, 2024). "Mitochondrial phosphoenolpyruvate carboxykinase (PEPCK-M; PCK2) is expressed in all cancer types examined and in neuroprogenitor cells." (PMID 33413684, 2021). "Taking together, our results suggest that HOTAIR is able to regulate the proliferation of cancer cells by modulating YBX1 nuclear localization, promoting in turn PCK2 and PDGFRB expression." (PMID 34266873, 2021). "PCK2 is a mitochondrial isoform of phosphoenolpyruvate carboxykinase (PEPCK) and is known to be overexpressed in multiple human cancers." (PMID 34266873, 2021). "Overall, these findings indicate that PURα promotes EMT and the transcriptional activation of the PCK2 gene in ESCC cells, while PCK2 can participate in the metabolic reprogramming of cancer cells." (PMID 33142842, 2020). "Taken together, these data demonstrate roles for PKM2, PC and PCK2 in HCC, which links metabolic flux and anabolic pathways to cancer cell proliferation." (PMID 28378759, 2017). "In total, 27 key metabolic enzymes were quantified in our study, including PCK2, PDH and G6PD, which are important for cancer development and progression." (PMID 28378759, 2017). "Given that acetyl-CoA is a major regulator of protein acetylation, and protein acetylation regulates cancer cell proliferation, survival, and even TIC maintenance, we examined protein acetylation in the PCK2-knockdown cells." (PMID 29137367, 2017). "Recently, S-nitrosylation of PCK2 and the upstream enzyme PC have been described to occur in different cancer cell lines in medium lacking glucose, in a manner dependent on nitric oxide production by the arginine-citrulline cycle." (PMID 33540663, 2021).
cancer (continued). "The combined PCK1 and PCK2 score was significantly elevated in NSCLC metastases compared to primary cancers, while the glycolysis marker GLUT1 showed no differential expression in metastases versus primary tumors." (PMID 32777161, 2020). "Our study suggests that inhibiting PCK2 may overcome the shortcomings of targeting PKM2 and may be therapeutically valuable for cancers with elevated PCK2 expression." (PMID 29137367, 2017). "Importantly, silencing of PCK2 significantly enhanced apoptosis rates of cancer cells cultured in glucose-restricted medium rather than in regular culture conditions." (PMID 39193344, 2024). "Indeed, cancer cells use FBP to suppress cancer cell growth partly by non-enzymatic mechanisms, while in ECs, PCK2 promotes growth, vessel barrier integrity and sprouting, partly through a role beyond its traditional role in GNG." (PMID 38783087, 2024). "We further revealed that PCK2-mediated gluconeogenesis removes abundance TCA cycle metabolites and restores redox balance in NSCLC cells upon glucose deprivation, showing the fine-tuning metabolic switches in cancer cells in response to nutrient-deprived tumor microenvironment." (PMID 39193344, 2024). "Thus, PCK1 or PCK2 enable cells to produce gluconeogenic/glycolytic intermediates for biosynthetic pathways that are essential for cancer cell proliferation in the absence of glucose." (PMID 33540663, 2021). "Thus, PCK1 or PCK2 enables the cells to produce glycolytic intermediates for biosynthetic pathways that are essential for cancer cell proliferation in the absence of glucose." (PMID 32777161, 2020). "This notion is further corroborated by another evidence showing that PCK2, but not PCK1, is highly expressed in different cancer cell lines." (PMID 32774674, 2020).
tumor (67 papers, 2013 to 2025). "Meanwhile, we also performed a correlation analysis between PCK2 and genes associated with different subtypes of tumor-infiltrating dendritic cells." (PMID 39744481, 2025). "Recent studies have implicated PCK2 in immune regulation, suggesting a potential link between PCK2 and tumor immunosuppression." (PMID 39744481, 2025). "Phosphorylation of ACSL4 by mitochondria-located metabolic kinase PCK2 is critical to regulating ferroptosis-associated phospholipid remodeling in tumor-repopulating cells that are resistant to chemotherapy and radiotherapy." (PMID 38720107, 2024). "PCK2 expression was significantly associated with a favorable outcome in LUAD also in multivariate survival analysis including tumor stage, grade, age at diagnosis, and gender." (PMID 32777161, 2020). "Importantly, the expression of cleaved caspase-3 and the number of TUNEL positive cells were increased in both A549-shPCK2 and H1975-shPCK2 tumor tissues, confirming that loss of PCK2 promotes apoptosis in NSCLC cells in vivo in the low glucose." (PMID 39193344, 2024). "Gene set variation analysis and CIBERSORT were used to explore the correlation of tumor-infiltrating immune cells according to PCK2 expression." (PMID 39744481, 2025). "By shedding light on this unexplored area, we hope to stimulate further investigations and pave the way for the development of novel therapeutic strategies targeting PCK2 and the tumor immune microenvironment in GBM." (PMID 39744481, 2025). "PCK2 was found to be downregulated in tumor‐repopulating cells and empowered resistance to ferroptosis in an ACSL4‐dependent manner." (PMID 39811936, 2025). "While PCK2's role in tumor metabolism has been increasingly recognized, its involvement in the modulation of the tumor immune microenvironment remains relatively unexplored." (PMID 39744481, 2025). "Consistently, we found that integrin β3+ tumor cells isolated from HONE1 tumors exhibited lower levels of pACSL4(T679) and PCK2 than those of integrin β3− tumor cells." (PMID 38720107, 2024). "PCK2 expression is elevated in a variety of human tumor types, including lung, breast, and prostate cancer, but the molecular mechanism of PCK2 in HCC is comparatively sporadic." (PMID 38890507, 2024). "By quantitative mass spectrometry analysis with anti-ACSL4 immunoprecipitates from lysates of HONE1 bulk tumor cells or TRCs, we identified kinases PCK2, PKM2 and PFKP, as well as phosphatase PPM1G, from the top 250 most enriched proteins in the precipitates." (PMID 38720107, 2024). "The correlation between PCK2 expression and immune invasion and checkpoint was found by utilizing Tumor Immune Estimation Resource (TIMER)." (PMID 38890507, 2024). "Of note, silencing of PCK2 significantly enhances apoptotic cell death in vitro and inhibits NSCLC tumor growth in a xenograft mouse model, indicating that PCK2-mediated gluconeogenesis is critical for NSCLC cells to override apoptosis." (PMID 39193344, 2024). "Intriguingly, increased PCK2 expression has been detected in tumor tissue of non-small-cell lung cancer patients." (PMID 37250903, 2023). "We show that PCK2 is required by CRC cells to optimally use amino acid L-glutamine to generate energy through the TCA cycle to support tumor cell survival and this is one mechanism used by PGC-1β and ERRα to promote the growth of CRC." (PMID 36230802, 2022). "lncHOTAIR regulates tumor cell proliferation by binding to Y-Box Protein-1 and promoting its nuclear translocation, which stimulates Y-Box Protein-1 downstream targets PCK2 and PDGFRβ." (PMID 36014574, 2022). "Recent reports have revealed that a potential role of PCK2 is to promote tumor growth and cell proliferation." (PMID 35982907, 2022). "qRT-PCR analysis further revealed that mitochondrial glutaminase 1 (GLS1), involved in tumor growth 44, and phosphoenolpyruvate carboxykinase (PCK2), which regulates tumor-initiating cells 45, were substantially downregulated by the depletion of KDM4B." (PMID 34335964, 2021).